IL6 (interleukin 6)
Diseases named in the same sentence as IL6 in open-access papers (continued):
Sharing a sentence is not in itself a finding about the gene and the disease.
tumor (continued). "As a well-defined cytokine, IL-6 is a type of interleukin that can be produced by fibroblasts, macrophages, T lymphocytes, B lymphocytes, endotheliocytes, keratinocytes, and a variety of tumor cells and has a wide range of functions in vivo." (PMID 35126308, 2021). "In addition to direct effects on tumor cells, IL-6 and JAK/STAT3 signaling can have a profound effect on tumor-infiltrating immune cells." (PMID 35155571, 2021). "Based on these discoveries, it is tempting to speculate that the transcriptional reprogramming initiated by CAF-secreted IL-6 or Wnt2 could shift the balance toward proangiogenic signals in favor of tumor angiogenesis and proliferation." (PMID 34660589, 2021). "A botanical drug called APG-157 containing multiple polyphenols suppressed tumor cells due to its antioxidant and anti-inflammatory properties, as demonstrated by reduced IL-1β, IL-6, and IL-8 concentrations in the salivary supernatant fluid of oral cancer patients." (PMID 34950252, 2021). "Recently it was show that ERK5 is requires for IL6 production in tumor cells." (PMID 35111744, 2021). "IHC demonstrated IL-6 expression in stromal compartments in both tumor types." (PMID 33851955, 2021). "In addition, pro-tumor macrophage phenotype decreased with a low level of IL-6, suggesting the anti-tumor role of the SuperMApo treatment." (PMID 35116038, 2021). "Numerous cytokines, including tumor necrosis factor-alpha, interleukin-1, interleukin-6, and interferon-gamma, released either by tumor cells or by the host as inflammatory reaction to tumor cells, have been postulated to play a role in the etiology of cancer cachexia." (PMID 34055649, 2021). "However, local mast cell-mediated IL-6 production during tumor development can act to enhance the process of DC mobilization and enable the transmigration of effector cells from the blood stream into local tissues." (PMID 33922465, 2021). "Moreover, the ADSCs recruited and located in the tumor microenvironment have the capacity of increasing IL-6 paracrine secretion by themselves." (PMID 34440886, 2021). "In addition to remodeling the ECM by MMPs, CAFs secrete VEGF, FGF, and IL6 to remodel the tumor vasculature and induce angiogenesis that is pivotal for tumor growth and metastasis." (PMID 34177890, 2021). "Furthermore, IL-6 blockade disrupted the anti-angiogenic efficacy of Bev and its concomitant anti-tumor activity." (PMID 33833265, 2021). "Moreover, inflammation is often described as the main inducer of angiogenesis during tumor growth, with IL-6 and IL-8 playing pivotal roles." (PMID 34903245, 2021). "Upregulation of MMP9 and IL-6 promotes tumour invasion, proliferation, apoptosis and metastasis." (PMID 33984826, 2021). "Activated TAMs promote tumor growth and immune tolerance via the NF-κB/IL-6 pathway." (PMID 34071550, 2021). "The upregulation of bone resorption results in a release of growth factors from the resorbed bone matrix (e.g., transforming growth factorβ (TGF-β) and Interleukin-6 (IL-6)), which themselves act as OAFs, OIFs, or can directly promote further tumour cell proliferation and survival." (PMID 34501423, 2021). "Functions of IL-6 production by malignant tumor cells are much less studied." (PMID 33851955, 2021). "IL-6 can lead to upregulation of PD-1 and immune exhaustion, while promoting interleukin 17 (IL-17) production – which can be a disadvantage in patients with cancer to subduing T-cell activity and augmenting tumor cell proliferation." (PMID 34335558, 2021). "The study aimed at assessing whether curcumin induces apoptosis of RCC and the involvement of AKT/mTOR pathway, the effects of curcumin on TNF-α, IL-6 and IL-8 cytokines, and finally, to understand the role of curcumin in autophagy and tumor-growth in vivo." (PMID 34402718, 2021).
tumor (continued). "Besides direct transcribing cell proliferation‐related genes, NF‐κB also induces the expression of proinflammatory cytokines such as IL‐1β, IL‐6, and TNFα, which play a key role in the NF‐κB‐dependent tumor cell proliferation." (PMID 34977871, 2021). "Interestingly, in mice, the knockout of SphK2 increased SphK1 and S1PR1 expression, providing a pro-inflammatory environment through the secretion of IL-6 and favoring the infiltration of macrophages and T cells into tumor tissues." (PMID 34744751, 2021). "IL‐6, a cytokine, was reported to support tumour cell invasion by inducing EMT effectively." (PMID 34464477, 2021). "The high IL-6 concentration could explain the reason for the significantly better survival of the tumor cells." (PMID 33922946, 2021). "Tumor-derived EVs can bind to soluble secreted cytokines and chemokines (i.e., CCL2 and IL-6) in the tumor microenvironment through their surface-expressed glycosaminoglycan (GAG) side chains of proteoglycans, significantly increase their uptake in the liver, spleen, and lung." (PMID 34616741, 2021). "Furthermore, IL-6 activation of the JAK/STAT3 pathway induces tumor cell survival by up-regulation/activation of anti-apoptotic proteins MCL-1 and BCL-XL, and c-MYC." (PMID 34067236, 2021). "IL-6 expression by MSCs is another mechanism supporting tumor resistance." (PMID 33472580, 2021). "Many intracellular signals are involved in protein turnover leading to muscle wasting, such as those signaling pathways activated by inflammatory cytokines, such as tumor necrosis factor alpha, interleukin-1 (IL-1), and IL-6, secreted by either immune or tumor cells." (PMID 34203023, 2021). "Moreover, MSC-secreted IL-6 has been shown to enhance tumor resistance by increasing the formation of CSCs." (PMID 34736460, 2021). "For instance, elevated levels of IL-6 are produced due to a positive feedback mechanism in the tumor microenvironment, which may regulate the persistent phosphorylation of STAT3 signaling in human cancers." (PMID 34771643, 2021). "In addition, activation of A2A receptor signaling by adenosine enhances the release of important cytokines, such as VEGF, IL-6, IL-10, and TGFβ, which suppress the inflammatory response and enhance tumor survival." (PMID 35127700, 2021). "CAFs also drive the recruitment of monocytes to the tumour site and their differentiation to the M2 macrophage phenotype which contribute to the tumour progression through secretion of pro‐inflammatory cytokines such as IL‐6, IL‐8, IL‐10 and TGF‐β." (PMID 33251764, 2021). "Moreover, in obesity, inflamed adipocytes create a proinflammatory microenvironment with infiltrating immune cells that foster tumor progression through proinflammatory mediators, such as IL6, IL8 and IL1β." (PMID 34685542, 2021). "Tumor-derived cytokines could also play a role in the upregulation of TF on monocytes as it was shown that DU145 cells release IL-6, which is a potent inducer of TF expression on monocytes." (PMID 33804899, 2021). "In addition, both GCSF and IL-6 stimulate angiogenesis and tumor growth by altering signaling pathways like STAT3 in neutrophils." (PMID 33923357, 2021). "In TME, IL-6 is a major contributor to the dynamic cross-talk between tumor cells and CAFs." (PMID 34722510, 2021). "Research on the effects of prescribing exercise in oncological patients is rapidly expanding, particularly after it was observed that voluntary running in tumour‐bearing mice suppressed tumour growth, likely by enabling IL‐6‐sensitive natural killer cells to infiltrate tumour tissue." (PMID 32478975, 2021). "IL-6 and IL-8 are involved in 3D formation in several tumour types." (PMID 34445479, 2021). "However, recent studies suggest that IL6 can also enhance anti-tumor immunity by resculpting T cell-mediated immune responses." (PMID 33550279, 2021).
tumor (continued). "Our data have shown that once the drug-resistant cells become the dominant tumor mass, the IL-6 level largely returns toward low level, although in drug-resistant tumors, the IL-6 level may be higher than before chemotherapy." (PMID 34588424, 2021). "Indeed, circulating levels of LCN2 are significantly reduced in both Myd88 and Il-6 knockout tumor-bearing mice." (PMID 33824339, 2021). "Tumor-associated macrophages have been demonstrated to contribute to the maintenance of breast CSC populations through triggering the production of the inflammatory cytokines interleukin 1 (IL-1), IL-6, and IL-8, which, in turn, reinforce the CSC states." (PMID 34912710, 2021). "However, IL-6 activity in cancer has not been completely understood, and its controversial roles in both tumorigenesis and tumor suppression have been reported." (PMID 33517609, 2021). "After treatment with propagermanium, the serum IL‐6, which participated in tumour angiogenesis, was downregulated in a dose‐dependent manner, suggesting that propagermanium may have the potential to inhibit angiogenesis and prevent cancer metastasis." (PMID 34464477, 2021). "In turn, secreted IL-6 and IL-8 by acid-stimulated OB may favor tumor progression in many different ways." (PMID 34124067, 2021). "Here we show that interaction with tumor microenvironment elements, mainly activated monocytes through IL-6 secretion, and the extracellular matrix protein fibronectin, induces the Stat3 transcriptional pathway and upregulates ODZ1 which results in GBM cell migration." (PMID 34376733, 2021). "Intratumoral co-injections of IL-6 significantly reduced the anti-tumor effects of cGAMP." (PMID 33790360, 2021). "Furthermore, in vitro co-culture models have shown that tumor cell-macrophage co-culture induced M2-like polarization via increased expression of IL-10, IL-12, IL-6, TNF-α, CCL5, CCL22, and CSF1." (PMID 34439281, 2021). "TNF-α, IL-6, IL-10, and TGF-β are secreted by neoplastic cells and tumor-associated macrophages." (PMID 34574650, 2021). "However, extracellular and tumor surrounding levels of IL-6 and IL-8 can more specifically help in distinguishing between benign and malignant conditions." (PMID 33906316, 2021). "Hence, it can be sum up that IL-6 generates a tumor environment by inducing the genes involved in cell proliferation." (PMID 34535145, 2021). "Priming with CpG attenuated Il6 and Nlrp3 expression, further upregulated expression of Nod2, Oas2, RhoA, Pycard, Tlr1/2 and Il12, and enhanced T-cell number and activation while polarizing macrophages to an anti-tumor phenotype." (PMID 33441763, 2021). "Accumulating evidence establishes IL-6 as a key player in supporting angiogenesis, where by inflammation may help drive tumor formation, growth, and metastasis." (PMID 34445494, 2021). "Based on the present data and previous reports, we propose that inhibition of the IL-6/STAT3 signalling pathway may promote the introduction of anti-tumour immunity into the tumour microenvironment." (PMID 34078370, 2021). "In the tumor microenvironment, TAMs are mainly the source of IL6." (PMID 33576874, 2021). "Notably, the acid-stimulated levels of expression of the inflammatory mediators and pro-osteoclastogenic factors IL-6 and IL-8 were significantly higher in hOB than in the tumor cell line MDA-MB-231 (p = 0.0339)." (PMID 34124067, 2021). "Importantly, two-way ANOVA demonstrated a significant interaction between DOX administration and the tumor on the serum levels of IL-6 and TNF-α." (PMID 34445729, 2021). "With this combination therapy (TZB+ATV), we can aim to directly improve the temporal trajectory of CRCC and to suppress tumor growth, through suppression of IL-6 and recovering apoptosis of cancer cells after chemotherapy, returning cognitive capability to the normal level." (PMID 34669701, 2021). "Moreover, oxaliplatin treatment of tumor-bearing rats induced the expression of the SASP factors IL6, IL8, CXCL1, CXCL2, and MMP." (PMID 33922007, 2021).
tumor (continued). "Studies have shown that IL-8, along with IL-6, TGF-β, and metalloproteinases, correspond to the major mediators produced by tumor-associated macrophages (TAMs) and is associated with angiogenesis, metastasis, and, consequently, tumor progression." (PMID 33921194, 2021). "However, all these responses are orchestrated by soluble mediators (e.g., chemokines and cytokines) including tumor necrosis factor alpha (TNF-α) and Interleukin-6 (IL-6) secreted by either host immune cells or tumor cells themselves." (PMID 34576335, 2021). "In conclusion, PLCG2 may affect IL-6/JAK/STAT3 signaling pathway to form anti-tumor TME, which may depend on the subtype of STS and the role of STAT3 in TME." (PMID 33725976, 2021). "In vitro analysis has revealed the involvement of IL-6 in the tumor invasion process." (PMID 34440475, 2021). "In the tumor microenvironment, the IL-6 signaling pathway activation results in a dual effect." (PMID 34576335, 2021). "Considering these promising results, IL-6 promoters, including rs1800795 and rs1800797, may be a tumor marker for cancer therapy." (PMID 34684062, 2021). "Further, corroborating our findings, LECs when treated with CCA-CM also showed increased gene expression of CXCL5 (p ≤ 0.0001) in addition to increased expression of critical inflammatory agents implicated in tumor-associated lymphangiogenesis such as IL1B, IL6, IL8." (PMID 34831316, 2021). "Importantly, classical SASP factors and NF‐κB targets, such as IL‐8, IL‐6, and metalloproteinases are constitutively expressed in these tumors, where they are suggested to fuel tumor growth and invasion." (PMID 33459422, 2021). "As a consequence, we can speculate that IL-6 also indirectly promotes tumor growth stimulating in paracrine fashion the tumor-surrounding cells to release pro-tumor mediators, including IL-6." (PMID 34576335, 2021). "The presence of senescent cells and IL6 in contralateral NIR A549 tumor mass led us to investigate if the AE observed could be ascribed to the release of specific molecules from IR cells endowed with SASP." (PMID 33673859, 2021). "IL-6 promotes tumor growth by inhibition of apoptosis and induction of tumor angiogenesis." (PMID 33467521, 2021). "Furthermore, elevated levels of IL-6 have been linked to tumors containing SASP cells and the regulation of IL-6 level has been shown to affect the anti-tumor immunity." (PMID 34141622, 2021). "In the AOM/DSS animal model, IL-6 deletion led to ameliorated tumor development." (PMID 33435303, 2021). "Thus, PDAC epithelial cells are a source of IL-6 in both the tumor micro- and macro-environment and apparently significantly contribute to cachexia and survival." (PMID 33851955, 2021). "It has been preliminary elucidated that IL-6 secreted by tumor cells could restrict the activity and function of NK cells through the JAK1 pathway." (PMID 34568032, 2021). "Researchers injected BMSCs into these mice models and observed reduced tumor cells which were derived by alleviated expression of proinflammatory cytokines such as TNFa, IL-6, and IL-1b and reduction of STAT3 activation by phosphorylation in colorectal tissues." (PMID 34249257, 2021). "The highest levels of serum IL-6, IL-10, and CRP were observed for the group administered with zotarolimus combined with 5-FU, and this was associated with the highest inhibition rate of tumor growth." (PMID 34361836, 2021). "IL-6 was reported to mediate various solid cancer behaviors, such as tumor growth and metastasis." (PMID 35111682, 2021). "Several studies show IL-6 and IL-8 secretion by cancer cells promote multiple drug resistance possibly via the autocrine induction of cancer stem-like cells while inhibiting these cytokines can re-sensitize the tumor against the chemotherapeutic drugs." (PMID 34307156, 2021). "The IL-6 in the TME induces MDSCs to mediate tumor immune escape through different pathways." (PMID 34527668, 2021).
tumor (continued). "When curcumin was orally administered before tumor development in combination with Listeria-Mage-b therapeutic vaccine, the production of IL-6 was significantly decreased, and IL-12 was increased by MDSCs in correlation with improved CD4+ T and CD8+ T cell responses in blood." (PMID 34948368, 2021). "CD4+ regulatory T cells, myeloid derived suppressor cells and macrophages (MØs) infiltrate early during PDA development, and directly promote tumour progression through matrix metalloproteinase (MMP) and IL6 signalling, while simultaneously suppressing anti-tumour immunity." (PMID 34921158, 2021). "Confirming TBK1 vs. IKKα/β dichotomy of mRIPO vs. LPS treatment, tumor homogenate cytokine analysis revealed stronger IKKα/β-driven cytokine induction by LPS (IL-6, TNF, IL-1β, IL-10), with CXCL10 (TBK1-dependent) being the most prominently induced cytokine after mRIPO treatment." (PMID 33767151, 2021). "Acute and transient inflammation may inhibit tumor growth by upregulating pro-inflammatory cytokines such as TNFα, IL-1β, and IL-6 that are part of the initial inflammatory cascade and recruit other downstream targets to enhance anti-tumor responses." (PMID 34975408, 2021). "Our findings are in accordance with the previous statements, as we found that both ADMSC and mature adipocytes secrete factors that could contribute to tumor development like IL6, EGF, PTGS2 and IL4 in ADMSC, and CCL5, IL1β and IGF in adipocytes." (PMID 33801973, 2021). "We hypothesize this attenuation of Il6 expression is one important component of generating an optimal anti-tumor immune response in the model studied here." (PMID 33441763, 2021). "IL-6 triggers the production of excess proinflammatory cytokines in the tumor microenvironment." (PMID 34001144, 2021). "Differences in cellular IL-6 responses among tumor types, study design, or clinical stage may explain these discordant results." (PMID 33833265, 2021). "IL-6 levels predicted recurrence, both by Kaplan–Meier survival analysis (p = 0.001) and utilizing a Cox multivariate regression analysis, with age, gender and tumor size additionally included as covariates (HR 7.13, CI 2.23–22.8; p = 0.001)." (PMID 32621022, 2021). "Given the resultant dysregulation and abundance of IL-6 in the tumour microenvironment, the inhibition of IL-6 as a therapeutic target in cancer progression may be beneficial." (PMID 34063891, 2021). "Regarding the role of IL-17, it was shown that this pro-inflammatory cytokine secreted by Th17 cells could facilitate tumor growth in vitro and in vivo through IL-6/STAT3 pathway in HBV-related HCC19." (PMID 34045534, 2021). "In the tumor microenvironment, elevated IL6/JAK/STAT3 signaling could suppress antitumor immune response and promote cancer cell proliferation, survival, invasiveness and metastasis." (PMID 34944787, 2021). "Furthermore, Il1β induces Il6 production, which promotes sustained, excessive inflammation, fostering a pro-tumor immune environment." (PMID 33441763, 2021). "Studies by Kim and colleagues also shown that tumor-derived IL-6 and IL-8 could be involved in mediating CTCs to re-infiltrate their original tumor, a process referred to as tumor-self seeding." (PMID 33809315, 2021). "Some studies have shown metformin could inhibit IL-6 secretion and decrease IL-6 signaling activation in tumor cells." (PMID 34881181, 2021). "Myofibroblastic CAFs (myCAFs) have a direct interaction with neoplastic cells and high expression of alpha-smooth-muscle actin (αSMA), while inflammatory CAFs (iCAFs) are located distally from the tumor cells and secrete high levels of IL-6 and some other cytokines." (PMID 34572947, 2021).